DUSP18 (dual specificity phosphatase 18)
Description:
Can dephosphorylate single and diphosphorylated synthetic MAPK peptides, with preference for the phosphotyrosine and diphosphorylated forms over phosphothreonine. In vitro, dephosphorylates p-nitrophenyl phosphate (pNPP). In bone tissue, upon activation of the G(q)-dependent KISS1/KISS1R signaling pathway, DUSP18 is recruited to the KISS1R C-terminus where it dephosphorylates SRC, resulting in down-regulation of osteoclast differentiation and activity, and consequently suppression of bone resorption (By similarity).
Synonyms: LMWDSP20; DUSP20; DSP18
Tractability: Antibody: UniProt places it where antibodies can reach, with medium confidence.
Gene: Protein-coding gene on chromosome 22 (30,652,051 to 30,667,887, reverse strand). Ensembl gene ENSG00000167065.
Subcellular location: Cytoplasm; Nucleus; Mitochondrion inner membrane
Subcellular location (Human Protein Atlas): Nucleoplasm
Gene Ontology:
Molecular function: phosphatase activity; protein binding; protein serine/threonine phosphatase activity; protein tyrosine phosphatase activity; protein tyrosine/serine/threonine phosphatase activity; MAP kinase tyrosine/serine/threonine phosphatase activity
Biological process: dephosphorylation; peptidyl-threonine dephosphorylation; peptidyl-tyrosine dephosphorylation; negative regulation of bone resorption; negative regulation of osteoclast differentiation
Cellular component: cytoplasm; nucleoplasm; nucleus; mitochondrial inner membrane
Genetic constraint (gnomAD): Loss-of-function variants: 6 observed, 12.03 expected, observed/expected ratio (o/e) 0.5, 90% interval 0.27 to 0.98. The upper end of that interval is the gene's LOEUF score, 0.98, which puts it in group 4 of 6, group 1 being the genes least tolerant of losing a copy. Missense variants: 235 observed, 261.47 expected, observed/expected ratio (o/e) 0.9, 90% interval 0.81 to 1. Synonymous variants: 96 observed, 100.09 expected, observed/expected ratio (o/e) 0.96, 90% interval 0.81 to 1.14.
Homologues: Orthologues: macaque DUSP18 (98% identical), dog DUSP18 (94% identical), pig DUSP18 (92% identical), guinea pig DUSP18 (87% identical), rat Dusp18 (85% identical), rabbit DUSP18 (84% identical), mouse Dusp18 (82% identical), chimpanzee DUSP18 (35% identical). Paralogues in human: DUSP21 (70% identical), DUSP14 (49% identical), DUSP26 (34% identical), DUSP1 (31% identical), STYXL2 (30% identical), DUSP8 (29% identical), DUSP16 (29% identical), DUSP29 (29% identical), DUSP13A (28% identical), DUSP4 (28% identical), DUSP13B (28% identical), DUSP6 (28% identical), and 19 more.
Diseases named in the same sentence as DUSP18 in open-access papers:
DUSP18 is named in the same sentence as 12 diseases in open-access papers, as found by Europe PMC text mining. Sharing a sentence is not in itself a finding about the gene and the disease. The quoted sentences say what the papers report.
colorectal cancer (2 papers, 2024 to 2025). A primary or metastatic malignant neoplasm that affects the colon or rectum. "In colorectal cancer, dual specificity protein phosphatase 18 (DUSP18) dephosphorylates and stabilizes the upstream stimulatory factor 1 (USF1) transcription factor, which subsequently induces the expression of the SREBF2 gene." (PMID 40270603, 2025). "DUSP18 mRNA expression was also upregulated in multiple colorectal cancer GEO datasets and some other cancer types." (PMID 38992029, 2024). "Here the authors show that inhibition of the dual-specificity phosphatase DUSP18 improves the activity of tumor-infiltrating CD8 T cells, enhancing response to immune checkpoint blockade in preclinical models of colorectal cancer." (PMID 38992029, 2024).
Alzheimer disease (1 paper, 2021). A progressive, neurodegenerative disease characterized by loss of function and death of nerve cells in several areas of the brain leading to loss of cognitive function such as memory and language. "Multiple GWAS studies reported that KCNT2 and DUSP18 are associated with Alzheimer disease, and KCNT2 is also associated with chronotype." (PMID 33314580, 2021).
kidney cancer (1 paper, 2024). Primary or metastatic malignant neoplasm involving the kidney. "Additionally, DUSP18 and SREBF2 mRNA levels were significantly positively correlated in TCGA-COAD, and pan-cancer analyses revealed a similar correlation in most tumors, including CRCs, liver and kidney cancers." (PMID 38992029, 2024).
prion disease (1 paper, 2020). A transmissible disease that is caused by a protein that is able to induce abnormal folding of normal cellular proteins, leading to characteristic spongiform brain changes, which are associated with neuronal loss without an inflammatory response. "The second, RPSA, is surface ribosomal protein that interacts with laminins (LAM), a dual-specificity phosphatase 18 (DUSP18), and prion protein 2 (PRND), which taken together may suggest various pathological processes such as prion diseases and cancer." (PMID 32624006, 2020).
cancer (2 papers, 2020 to 2024). A tumor composed of atypical neoplastic, often pleomorphic cells that invade other tissues. "Considering this, we suggest that future pre-clinical studies aimed at targeting DUSP18 in cancer therapy be conducted in immune-competent backgrounds." (PMID 38992029, 2024). "Our study found that, in cancer cells, DUSP18 affects cancer progression through its influence on USF1-SREBP2-driven transcriptional cascade that increases micro-environmental lanosterol and blocks CD8+ T cell activation." (PMID 38992029, 2024). "Mechanically, DUSP18 increases the activity of the USF1-SREBP2 transcription factor (TF) axis, upregulates the cholesterol biosynthetic pathway and allows for the accumulation of lanosterol, a cholesterol precursor, in cancer cells." (PMID 38992029, 2024).
tumor (1 paper, 2024). "Tumor samples with high DUSP18 expression had lower immune-related indicators scores, lower tumor mutation burden, microsatellite instability, tumor neoantigens and mutant-allele tumor heterogeneity." (PMID 38992029, 2024). "Overall, these findings support the notion that DUSP18 exerts control over the tumor-associated immune landscape by regulating cellular cholesterol biosynthesis." (PMID 38992029, 2024). "Here, we report CRISPR screens in a mouse model of colo-rectal cancer (CRC) that implicates the dual specificity phosphatase 18 (DUSP18) in the establishment of tumor-directed immune evasion." (PMID 38992029, 2024). "Given that DUSP18 plays an important role in tumor immune evasion, we attempted to identify DUSP18 inhibitors to use as potential CRC therapies." (PMID 38992029, 2024). "Taken together, our observations have revealed a crucial role for DUSP18/USF1/SREBF2-lanosterol signaling in tumor immunosuppressive reprogramming." (PMID 38992029, 2024). "Since Dusp18 mediates tumor immune evasion in a CD8+ T cell-dependent manner, the cytotoxic killing of B16-OVA-Luc and MC38-OVA-Luc cells (expressing Ovalbumin and Luciferase) by OT-I T cells was measured in an in vitro killing system." (PMID 38992029, 2024). "The effect of Dusp18 inhibition on the tumor immune landscape was further explored using flow cytometry." (PMID 38992029, 2024). "In contrast tumor samples with low DUSP18 expression showed higher enrichment scores of T cell inflammatory gene expression profile, innate anti-PD-1 resistance, immuno-predictive score signatures and PD-1 response signatures." (PMID 38992029, 2024). "Collectively, these findings demonstrated that DUSP18 in tumor cells suppresses CD8+ T cell activation and cytotoxicity and promotes CD8+ T cell exhaustion." (PMID 38992029, 2024). "The results showed that low DUSP18-expressing tumor samples were significantly enriched for immune-related functions pertaining to antigen presentation, chemokine signaling, T-cell receptor signaling, whereas high-expressing samples were enriched for cholesterol biosynthetic pathways." (PMID 38992029, 2024). "Notably, silencing Dusp18 resulted in a deceleration of xenograft tumor growth, accompanied by increased levels of IFN-γ and GzmB expression, and a decrease in the percentage of PD-1+, TIM-3+, and CTLA-4+ CD8+ T cells." (PMID 38992029, 2024). "Thus, our findings suggested that CD8+ T-cell-mediated immunity is involved in some aspect(s) of DUSP18-regulated tumor growth." (PMID 38992029, 2024). "However, Dusp18 inhibition did impair tumor growth and prolonged survival in immunocompetent mice although depleting CD8+ T cells completely eliminated this growth disadvantage." (PMID 38992029, 2024). "The results showed that some genes with the potential to promote tumor immune evasion, such as Ptgs1 and Dusp18, etc., were significantly enriched in all three analytical methods, which excludes the effect of different analytical methods on the differences in results." (PMID 38992029, 2024). "We next co-cultured tumor cells and CD8+ T cells to explore the effect of Dusp18 inhibition on CD8+ T cell activation, effector function, and expression of exhausted-related molecules." (PMID 38992029, 2024). "Given that Lumacaftor can inhibit DUSP18 activity and enhance the antitumor function of CD8+ T cells in vitro, the antitumor effect of Lumacaftor were subsequently assessed on tumor models in vivo." (PMID 38992029, 2024). "Because CD8+ T cells must recognize MHC-I molecules on the surface of tumor cells prior to initiating tumor cell killing (MHC restriction), the effect of Dusp18 inhibition on tumor cell antigen presentation was examined." (PMID 38992029, 2024). "After MC38 cells overexpressing wild-type (WT) or phosphatase dead mutant (Dead) Dusp18 were inoculated into mice, only the former promoted tumor growth in immunocompetent mice but not in nude mice." (PMID 38992029, 2024).
tumor (continued). "Finally, the combination of an anti-PD-1 antibody and Lumacaftor, an FDA-approved small molecule inhibitor of DUSP18, inhibits CRC growth in mice and synergistically enhances anti-tumor immunity." (PMID 38992029, 2024).
DUSP18 also shares sentences with these, for which no sentence is quoted: bipolar disorder (1 paper); colon cancer (1); insomnia (1); melanoma (1); neurological diseases (1); Parkinson disease (1).